MYC (MYC proto-oncogene, bHLH transcription factor)
Diseases named in the same sentence as MYC in open-access papers (continued):
Sharing a sentence is not in itself a finding about the gene and the disease.
tumor (continued). "The majority of miRNAs, including members of the let-7 family, were detectable at low levels and then increased upon tumor regression as early as 3 days after MYC inactivation even though tumors did not fully regress until after 14 days." (PMID 18826639, 2008). "For instance, it has been suggested that the amplification of oncogenes on chromosome 8q (i.e., c-MYC and EBAG9) may support tumour progression." (PMID 18728668, 2008). "When the sHEL-recognizing B cells from these mice were transplanted into C57/B6 recipients, tumours did not develop even in the absence of doxycycline (when the MYC gene is expressed constitutively) due to the lack of sHEL expression." (PMID 18578571, 2008). "Although a copy number gain would also be expected for the tumours analysed in the present study, we found a negative correlation of MYC immunostaining and tumour progression." (PMID 17146477, 2007). "Not surprisingly, the one tumor with 8q23-q24 amplification displayed the highest MYC level, while low copy number gains of 8q did not correlate with higher MYC levels in either microarray- or qRT-RTPCR-tested specimens." (PMID 16968546, 2006). "In contrast, in adult mice MYC overexpression induced cell growth and DNA replication without mitotic cell division, and mice succumbed to neoplasia only after a prolonged latency." (PMID 15455033, 2004). "We conclude that apoptosis is not the mechanism that precludes MYC from inducing neoplasia in hepatocytes." (PMID 15455033, 2004). "We found that MYC activation in adult mice that have undergone partial hepatectomy exhibited a reduced latency of tumor induction in comparison with adult mice that had not undergone surgery (mean latency of 14 weeks versus 35 weeks)." (PMID 15455033, 2004). "Activation of human c-myc has been shown to be a common event in intermediate- and high-grade NHL and so the recurrent gain of CFA 13 observed in this study suggests that it is crucial to examine the potential involvement of c-MYC and c-KIT in canine tumour development." (PMID 14562028, 2003). "In RNA dot blot assays the expression of KRAS2, PDGFA, EGFR, or MYC was generally not increased in the tumour samples when compared to that in normal testicular tissue of the same patients although there was interindividual variation in mRNA levels." (PMID 1829952, 1991). "Besides frequent MYC MED30 co-amplification, MED30 overexpression alone is sufficient to enable MYC occupancy and activation of previously weak or unbound enhancers and promoters, driving tumor-promoting gene expression." (PMID 42275218, 2026). "For example, patients with NF1 A26465S (0.6%) at baseline experienced an 11% tumor reduction after 4 months of sotorasib treatment, and patients with SCLC with treatment-emerging NF1 N1004Ifs∗8 (0.3%) progressed with a 58% increase in tumor size, accompanied by MYC amplification (3.5-fold)." (PMID 41541668, 2026). "Hence, by suppressing MYC oncogenes, encouraging activation of cGAS‐STING pathway may help to sensitize tumour to PD‐L1‐targeted immunotherapy." (PMID 41492185, 2026). "In contrast, oncogene expression in the tumour-resistant population (Ivl-BRAFV600E-tdRFP) exhibited high pSTAT3 levels at early time points, but these diminished and became limited to small clones by day 28, with only weak MYC activation observed across the time course." (PMID 41507151, 2026). "Unlike primary tumor cells, tumor cells in brain metastases may harbor mutations in genes such as ERBB2, BRAF, MYC, and BRCA2." (PMID 39780275, 2025). "Similar to other DOCK family members such as DOCK2—which exhibits either tumor-suppressive or tumor-promoting roles depending on the specific tumor context and immune microenvironment—DOCK4 is involved in diverse signaling pathways in LUAD, including MYC signaling and DNA repair." (PMID 40529490, 2025).
tumor (continued). "The tumor types examined here also do not encompass the full range of MYC-driven cancers, and it remains to be seen how broadly our findings may be applied to other malignancies." (PMID 40668928, 2025). "Additionally, amplification of the MYC gene family is frequently observed in small-cell lung cancer (SCLC), resulting in elevated expression of the c-MYC oncoprotein, which drives cellular survival, proliferation, and tumour progression." (PMID 40256842, 2025). "Additionally, it has been reported that MYC upregulation could promote the transcription of lipid metabolism genes and synergize with SREBP1 to regulate lipid synthesis in tumor cells." (PMID 40025540, 2025). "Could the scenario that some but not all tumor cells, depending on an upregulated MYC gene expression, form epichaperomes pan out in the CSC population?" (PMID 39936995, 2025). "The SCF ubiquitin ligase substrate recognition subunit F-box/WD repeat-containing protein 7, FBXW7, is a well-known tumour suppressor, initiating the ubiquitination and subsequent degradation of many cell cycle-regulated proteins, including oncogenes such as CCNE1(cyclin E), MYC and RICTOR." (PMID 40276932, 2025). "Furthermore, PP2A regulates c-MYC by dephosphorylating key residues, with PP2A-B55α targeting S62 to stabilize c-MYC and PP2A-B56α targeting T58 to promote its degradation, thus regulating tumor growth." (PMID 41146310, 2025). "Consistent with this hypothesis, the patient manifesting with late F‐NHL relapse originated from DLBCL with typical molecular and IHC profile of a GCB neoplasm with BCL2 but not MYC re‐arrangements." (PMID 40838116, 2025). "c-MYC was elevated suggesting that RRM2-OE-TPC-1 cells may achieve the synergistic activation of multiple proliferative signaling pathways with the help of this transcription factor, accelerating tumor progression." (PMID 41333212, 2025). "c‐MYC, an oncogenic transcription factor, promotes the EMT process by regulating key markers, including downregulating E‐cadherin and upregulating N‐cadherin, while also interacting with multiple signaling pathways to enhance the invasive and metastatic potential of tumor cells." (PMID 41244070, 2025). "We found that indisulam treatment promoted a remarkable infiltration of NK cells in the c-MYC tumors implanted in Rag2-/- mice, and various immune cells, including T and NK cells in the transgenic TH-MYCN/ALKF1178L tumors, suggesting that indisulam induced an “inflamed” tumor microenvironment." (PMID 40962798, 2025). "However, ONT-based methylation profiling classified the tumor as ATRT, subclass MYC subgroup." (PMID 41180011, 2025). "By leveraging high-throughput proteomic profiling (Nanostring GeoMx®) and circulating tumor DNA (ctDNA) monitoring, we identify actionable targets for HAL-specific precision therapy, such as EBV-directed CAR T-cells or PD-1 blockade in combination with MYC inhibition." (PMID 40496610, 2025). "Neither approach altered MYC‐overexpression induced subcutaneous tumor rapid proliferation." (PMID 39899538, 2025). "Furthermore, MYC activation exerts dual immunosuppressive effects by downregulating JAK2 expression, thereby attenuating both type I and type II IFN signaling cascades and diminishing tumor cell responsiveness to interferon stimulation." (PMID 40303413, 2025). "Notably, MYC binding to PANK1–3 promoters is prominent in the pre-tumoral and tumor samples but absent in the matched normal tissue, suggesting a tumorigenesis-related CoA biosynthesis induction by MYC." (PMID 40832336, 2025). "Public data from the IMpower133 trial further validated the chemo‐resistant role of the MYC‐Notch‐non‐NE axis and highlighted the importance of the inhibitory Notch ligand, DLL3, in predicting response to chemo‐immunotherapy and promoting an immune‐supportive tumor phenotype." (PMID 39974662, 2025). "Notably, while miR-218 mediates Notch-induced MYC suppression in TECs, it fails to reduce tumor growth." (PMID 40303332, 2025).
tumor (continued). "Additionally, the lack of genome sequencing and MYC rearrangement on tumor samples is another limitation." (PMID 40538656, 2025). "The association between c-MYC and ALDH1A1 positivity and favorable prognosis of ITAC suggest that rather than having a role in stemness, these factors act as tumor suppressors and may be used as markers of prognosis and response to treatment in ITAC patients." (PMID 41463190, 2025). "However, in vitro studies reveal that the knockout or knockdown of MYC in numerous tumor cell lines does not necessarily result in cell death, despite these tumors exhibiting MYC addiction in vivo." (PMID 40732268, 2025). "Thus, it is not surprising that if our tumor were to match to a particular subset of AT/RT, the MYC-activated subtype should be the class where it best belongs." (PMID 39833894, 2025). "Targeting MYC and FBL could provide a therapeutic approach to reduce CRC tumor growth." (PMID 41463151, 2025). "Approaches that indirectly target MYC, such as epigenetic modulators or inhibitors of its cofactors, could complement RTK-targeted therapies by disrupting the synergistic feedback loop and limiting tumor adaptability." (PMID 40076599, 2025). "The tumorigenesis of SPN may be closely related to oxygen metabolism, MYC targets, and DNA repair;SPN tumor cells may originate from pancreatic endocrine progenitor cells;NOV, DCN were nominated as primary and S100A10, MGP as recurrent SPN marker genes, respectively." (PMID 40312910, 2025). "Recent studies by the Eilers group added further nuance: MYC protein has been observed to multimerize at stalled replication forks, and MYCN can recruit the nuclear exosome targeting complex to nascent RNAs leading to S phase progression and tumour cell stress resilience." (PMID 41561634, 2025). "In particular, gene sets related to E2F, G2M and MYC targets emerge as upregulated, while gene sets related to antibody recognition such as gamma-interferon responses, EMT, allograft rejection emerge as downregulated, suggesting that CTCs are immune-evading tumor cells." (PMID 40157906, 2025). "Moreover, Gene Set Variation Analysis (GSVA) revealed that upregulated genes in EPI_M versus EPI were enriched in pathways related to tumor invasiveness, hypoxia, EMT, MYC target, and G2 M checkpoint, while downregulated genes were enriched in metabolic pathways." (PMID 39950944, 2025). "We found that among the 57 c-MYC target genes showing decreased expression after EM127 treatment, 12 (21%) are known to be oncogenes, whereas among the 111 c-MYC target genes showing increased expression after EM127 treatment, only 1 (1.11%) is known to be a tumor suppressor in CRC." (PMID 40588481, 2025). "Indeed, certain targeted therapies could even be applied to multiple tumor types as seen in HDAC inhibitors for SHH-MB, MYC-amplified G3-MB, and DMG." (PMID 40599851, 2025). "Thus, despite in vitro findings of Nef-induced BCL2 upregulation, in vivo HAL tumors may preferentially activate alternative survival pathways such as LMP1-driven NF-κB/PI3K/AKT signaling and MYC amplification, reducing dependency on BCL2 for tumor survival." (PMID 40496610, 2025). "Furthermore, UBE3A haploinsufficiency in an MYC-driven B-cell lymphomagenesis model increased PML levels, induced cellular senescence, and suppressed tumor progression, which is consistent with elevated levels of UBE3A and decreased levels of PML in primary B-cell lymphoma samples." (PMID 40002221, 2025).
tumor (continued). "In fact, WDR5 also interacts with MYC, a well-known oncoprotein broadly overexpressed in some cancers, through its WBM site to promote tumorigenesis, and other proteins through its WIN site and these interactions are extensively reported to be involved in tumor progression." (PMID 38744853, 2024). "To determine whether I3P rescues tumor growth of MYC-ON Trp-starved mice, we supplemented MYC-ON mice fed the No-Trp diet with daily IP injections of either vehicle or I3P." (PMID 38769298, 2024). "Thus, short-term therapeutic inhibition of the nucleocytoplasmic transport gene, Xpo1, induces tumor regression without affecting normal adjacent liver in an autochthonous transgenic mouse model of MYC-induced HCC." (PMID 38302473, 2024). "21: 8,208,473–8,208,652) may play a role as a tumor-suppressive miRNA within the MIR-3648/FRAT1-FRAT2/MYC negative feedback loop." (PMID 38932267, 2024). "On the other hand, NCAPD3 increased the expression of transcription factor MYC, which directly inhibited miR-30a-5p transcription via binding its host gene LINC00472 promoter region, both of which promoted cell proliferation and migration and accelerated tumor growth in PCa." (PMID 38561330, 2024). "Further investigation revealed that this interesting phenomenon may be related to R-2HG, a metabolite of IDH, compound 39 (R-2HG, FTO IC50 = 133.3 μM) can affect the FTO/m6A/MYC/CEBPA pathway and inhibit tumor proliferation and survival by repressing the expression of FTO." (PMID 38711100, 2024). "Ma and colleagues identified MYC as a negative regulator that impeded the migratory and invasive capacity mediated by Ras and Lgl and decreased expression of the JNK signaling target, matrix metalloproteinase (MMP-1), thereby interfering with tumor migration and metastasis." (PMID 37450923, 2024). "Therefore, 1808 MYC-SL genes were identified that had essential functions in MYChigh but not MYClow tumor cells." (PMID 38302473, 2024). "In contrast, the MYC-Cdh1−/− tumors displayed undifferentiated histology along with the expected absence of E-cadherin expression and lack of normal cell–cell adhesion between tumor cells." (PMID 38177458, 2024). "It has been established that MYC interactions with several chromatin remodellers, including SWI/SNF complex, contribute to its efficiency in regulating gene expression related to metabolism, angiogenesis, invasion, tumour microenvironment, protein synthesis and cell proliferation." (PMID 39471843, 2024). "The results showed a significant correlation between the SHMT2 gene and tumour proliferation, DNA repair and replication, cellular cycle, and MYC genes, which suggested that SHMT2 might be involved in the appearance and development of tumours in a variety of processes." (PMID 38188143, 2024). "Finally, the expression of two COAD stemness‐related markers, ALDH1A3 and c‐MYC, was reduced in spheroids treated with GCN2i, confirming that GCN2 is essential for the viability of c‐Myc‐expressing tumor cells and the elimination of quiescent tumor cells in the presence of the drug." (PMID 37452637, 2024). "The effect of JQ1 was directly proportional to the expression of MYC, regardless of whether the tumour was of embryonal or alveolar origin." (PMID 38191874, 2024). "c‐MYC, which has the overall structure and organization of genes and transcripts similar to MYCN, may be responsible for partial response to ceftriaxone of tumor cells expressing the c‐MYC rather than MYCN." (PMID 37975412, 2024). "Functional enrichment analysis of the UPP1high tumor cell population demonstrated these cells were related to cancer-related biological processes, including Tumor_Invasiveness, PI3K/AKT/mTOR_signaling_pathway, MYC_targets, MAPK_signaling_pathway, as well as TGFβ_signaling_pathway." (PMID 38331898, 2024).
tumor (continued). "MYC overexpression induces an immunosuppressive TME through the release of chemokines, growth factors, and inflammatory cytokines, as well as promoting activation of anti-immune checkpoint proteins, such as CD47, HIF, and TRVP1, in tumor cells to suppress M1 and M2 macrophage activation." (PMID 37450923, 2024). "In tumor cells, MYC expression is often elevated and no longer controlled by mitogenic signaling." (PMID 38443386, 2024). "Among the immunoprecipitate identified by MS, the focus of attention was MYC proto-oncogene, bHLH transcription factor (c-Myc), which can regulate the transcriptional expression of PDL1 by binding to the PDL1 promoter and act as an essential motor of tumor growth and immune evasion." (PMID 38302412, 2024). "In addition, analysis of tumor transcriptomes suggests that induction of EMT, SMAD protein signal transduction, reorganization of extracellular matrix and vasculogenesis are enriched in FGF19/Aldafermin + MYC driven tumors." (PMID 38228803, 2024). "In 13 of 16 (81%) discrepant samples, MYC expression varied between 25 and 50%, and the observers agreed with that it was difficult to determine whether the tumor cells were over or not the cutoff defined for MYC." (PMID 37368083, 2024). "Therefore, the impact of non-classical c-MYC functions on the maintenance of genomic stability appears crucial in tumor genesis." (PMID 39594704, 2024). "Furthermore, we investigated whether these results could be captured in the genetically engineered mouse model (GEMM) tumor organoid-derived cells, AKTP 1C9 and 2A6, which express MYC at similar levels to those of CMT167 and CT26." (PMID 38992694, 2024). "Preoperative MYC amplification may have a strong prognostic impact but cannot be determined without a preoperative needle biopsy from the tumour." (PMID 38536546, 2024). "In situ sequencing also confirmed a consistent pattern: in EpCAMhigh tumor cell-dominated spots, compared to EpCAM-negative cell-dominated spots, there was a more frequent expression of the CD133/PROM1 gene along with the transcription factor genes OCT4/POU5F1, KLF4, and MYC." (PMID 39456890, 2024). "However, mutations, long ncRNAs, and LINE-1 sequence insertions in the canine c-MYC promoter have also been reported in CTVT, suggesting that these factors may also play a role in tumor senescence and progression [1, 9−11, 19, 28]." (PMID 39185058, 2024). "Hence, ATRA responsiveness appears not to be restricted to MYC(N) amplification nor growth kinetics in a given tumour model but rather favours embryonal tumours of the nervous system with synaptic vesicle formation capacity." (PMID 38942989, 2024). "Next, we further determined whether the ablation of Tsc2 alone could also accelerate c-MYC tumor development without MCL1." (PMID 39325536, 2024). "Despite the increase in MYC target expression in CTDNEP1-deficient cells, MYC mRNA levels were not substantially altered in D425 tumor cells treated with shCTDNEP1 RNAs, suggesting that CTDNEP1 might regulate MYC signaling post-translationally." (PMID 36765089, 2023). "In addition, this inhibitor showed promise for the treatment of MYC-amplified NB, evinced by apoptosis induction in vitro and dose-dependent growth inhibition in PDX, with improved survival and tumor regression in 86% of patients 7 days of treatment initiation." (PMID 36839989, 2023). "Importantly, copy number analyses also indicated heterogeneity, with an MYC amplification seen in the CSF cfDNA but not the primary tumor, later emerging at the time of relapse (patient 17)." (PMID 37444642, 2023). "The highest MYC copy number in tumor samples was 14.41 in contrast to 2.14 in non-tumor samples." (PMID 37858127, 2023).